IL31 (interleukin 31)
Diseases named in the same sentence as IL31 in open-access papers (continued):
Sharing a sentence is not in itself a finding about the gene and the disease.
tumor (continued). "The interplay between IL-31, IL-33, eosinophils, and the tumor microenvironment (TME) could significantly influence immunotherapy outcomes in NSCLC, and understanding these mechanisms is crucial for enhancing therapeutic efficacy and overcoming treatment resistance." (PMID 40305195, 2025). "STC1 may influence CD4+ T cells to secrete cytokines, including IL-17, IL-31, and IL-33, which modulate immune responses via autocrine or paracrine mechanisms, thereby either amplifying or suppressing immune activity within the tumor microenvironment." (PMID 39201771, 2024). "IL-31 seems to play an important role in the signalling pathway involved in pruritus, but it is also suggested to play a proinflammatory and immunomodulatory role which could play a part in the progression of the neoplastic disease." (PMID 34118946, 2021). "Moreover, the tumor growth in mice can also be inhibited by the administration of exogenous IL-31." (PMID 29484036, 2018). "However, additional studies are required to assess the pro-inflammatory and immunomodulatory effects of IL31 in the tumor microenvironment, and whether such activities affect tumorigenesis." (PMID 28147314, 2017). "However, the contribution of IL31 to tumor progression or metastasis is still elusive." (PMID 28147314, 2017). "The expression level of IL-31 in serum was measured by ELISA, while the abundance of FAP+CAFs in tumor tissues was assessed via IHC." (PMID 40843362, 2025). "To determine the net effect of IL-31 on the immune state in the TME, we evaluated the levels of a repertoire of Th1/Th2 cytokines in whole tumor lysates of PyMT-ev and PyMT-IL-31 tumors." (PMID 32843492, 2020). "We found that IL31 and its receptor IL31RA are differentially expressed by various tumor types from both human and mouse origins." (PMID 28147314, 2017). "A question raised by this study is how IL-31 and TSLP can modulate the HL lymph node microenvironment to support tumor growth." (PMID 29156718, 2017). "Tumor growth, percentage of endothelial cells and MVD in tumors were significantly reduced in mice infused with IL31 compared to control mice, similar to our findings with MC38 tumors." (PMID 28147314, 2017). "We found that IL31 and IL31RA are expressed by several types of tumor cells from both mouse and human origins." (PMID 28147314, 2017). "Here, we investigated the expression of IL31 and its receptor (IL31RA) in various cancer cell lines and human tumor specimens." (PMID 28147314, 2017). "We show that IL31 and its receptor, IL31RA, are highly expressed in various human and mouse cancer cell lines, as well as in tumor specimens from cancer patients." (PMID 28147314, 2017). "Comparing with the tumor markers of CEA, CA-125, and CA19-9, the serum IL-31 is still equipped with a better sensitivity (92.68%) and specificity (94.87%), using a cut-off value at 113.1 pg/mL." (PMID 27340318, 2016). "The intraperitoneal injection of IL-31 in a murine breast cancer model resulted in CD8+ T-cell infiltration, which led to an immune response against tumor cells; better survival was also demonstrated due to the modulation of the release of cytokines like IL-10 and IL-2." (PMID 40305195, 2025). "We confirmed that IL-31 levels were increased only in tumor lysates of PyMT-IL-31 primary tumor and not in PyMT-ev, PyMT-wt(ev) and PyMT-wt(IL-31) as well as in the plasma of PyMT-IL-31 tumor-bearing mice." (PMID 32843492, 2020). "It is plausible that IL31, like other pro-inflammatory cytokines, alters tumor cell activity by inhibiting cell motility rather than increasing it, explaining its inhibitory effect on angiogenesis and metastasis." (PMID 28147314, 2017). "In addition to recapitulating known alterations, MutComFocal identifies ARID1B, ROBO2 and MRS1 as candidate tumor suppressors and KLHL6, IL31 and LRP1 as putative oncogenes in DLBCL." (PMID 23531283, 2013).
tumor (continued). "Similarly, macrophages in metastatic UVM showed strong enrichment for cytokines like Adiponectin, Prolactin, IL7, IL10, IL15, IL9, IL31, APRIL, Persephin, and IL22, highlighting their role in creating a pro-tumorigenic environment through immune modulation and support of tumor growth." (PMID 39916959, 2024). "In contrast, IL-31 blockade resulted in modest tumor suppression in the CAF-containing model, indicating that CAF-derived IL-31 likely exerts its effects by shaping an immunosuppressive microenvironment rather than driving tumor proliferation per se." (PMID 40843362, 2025). "In addition, we have investigated the expression of IL-31, TSLP and their receptors in invaded lymph nodes from HL patients in view of the tumor promoting role of these cytokines and the complete lack of information on this latter issue." (PMID 29156718, 2017).
cancer (18 papers, 2013 to 2025). A tumor composed of atypical neoplastic, often pleomorphic cells that invade other tissues. "For example, polymorphisms in IL-31 have been associated with the development of diseases and cancer." (PMID 29484036, 2018). "A few reports in the literature have recently implicated the IL-31/IL31RA axis in cancer." (PMID 33553434, 2021). "In recent years, a few literatures implicated the involvement of the IL-31/IL31RA axis in cancer." (PMID 32528891, 2020). "Herein, we provide un updated literature review on the role of eosinophils in cancer development and immune response, and the functions of some cytokines, including IL-31 and IL-33, in eosinophil activation." (PMID 40305195, 2025). "In particular, the activity of IL-31 and IL-33 seems to be crucial in the formation of an immune response against cancers." (PMID 40305195, 2025). "Lastly, the ability of WISIT vaccine-induced Abs to suppress IL-31 signaling was assessed using A549 cells, a human epithelial carcinoma cell line expressing both hIL-31RA and OSMR, which are required for IL-31 signaling induction." (PMID 39932924, 2025). "More recently, different authors have reported the antiproliferative and antiangiogenic role of IL-31 in cancer cells." (PMID 35742951, 2022). "Therapy with mogamulizumab, a monoclonal-antibody anti-CCR4, promotes a reduction in cancer-cell populations, followed by a decrease in IL-31 levels and itching." (PMID 35742951, 2022). "Another key objective of this research was to examine the content validity and relevance of a potential new PRO measure (EORTC IL31) designed to be used alongside a well-established cancer PRO measure (EORTC QLQ-C30) in a clinical trial setting." (PMID 35507231, 2022). "In fact, one of the messages of this review is to stimulate researchers in linking itch in various type of cancer and testing the role of the “skin neuroimmune cytokine” IL-31." (PMID 34118946, 2021). "IL-31 has also been found to be increased in some cancers, such as breast cancer, whose main metastatic location is the skeleton." (PMID 32069819, 2020). "To test the potential therapeutic effect of IL-31 in human-relevance cancers, we used IL-31-IgG fused protein with extended half-life and demonstrate its therapeutic potential in vivo when used in combination with chemotherapy." (PMID 28147314, 2017). "Overall, our results demonstrate the potential use of IL31 as a novel antiangiogenic drug for the treatment of cancer." (PMID 28147314, 2017). "In this study we investigated the role of IL31 in cancer progression focusing on processes other than immunomodulation." (PMID 28147314, 2017). "More following evidences have proved that IL-31 and IL-33 play an important role in some cancers' formulation, like lung cancer, gastric cancer, and squamous cancer." (PMID 27340318, 2016). "Some authors related IL-31 levels to itching severity and the stage of cancer." (PMID 35742951, 2022). "The IL-31/33 axis role in pruritus in malignancies should be deeply investigated." (PMID 34118946, 2021). "We therefore investigated whether IL-31 expression correlates with good prognosis in patients with cancer as well." (PMID 32843492, 2020). "There is only limited evidence for the involvement of IL31 in cancer." (PMID 28147314, 2017). "We next investigated the effect of IL31-IgG in human models of cancer using NOD-SCID mice." (PMID 28147314, 2017). "We should note that the use of NOD-SCID mice, which are deficient of immune cells, allowed us to rule out the cancer associated inflammation that may take place following IL31 therapy inflammation." (PMID 28147314, 2017). "The EORTC IL31 Disease Symptoms PRO instrument is based on preexisting, validated cancer instruments and covers symptoms considered most likely to be relevant to the patient population based on literature review and clinical input." (PMID 35507231, 2022).
cancer (continued). "The EORTC IL31 was developed to be used as an mSS-specific add-on to the EORTC QLQ-C30, which evaluates general cancer and treatment-related symptoms and functioning." (PMID 35507231, 2022). "In contrast, blocking individual cytokines (IGFBP-3, IGFBP-2, VEGF, PDGF-AA, IL-6 or IL-31) in A549-fibrocyte co-culture CM using neutralizing antibodies decreased ET1 and ETA on cancer cells." (PMID 36241617, 2022). "Thus, IL-31 may potentially be used as an antiovarian cancer drug to treat the disease." (PMID 29484036, 2018). "Furthermore, stimulating cancer cells with recombinant IGFBP-3, IGFBP-2, VEGF, PDGF-AA or IL-31 led to upregulation of ET1 and ETA." (PMID 36241617, 2022). "The researches collected together with other reports were not able to clarify if interleukin 31 is connected to the itch, to the cancer or to both." (PMID 34118946, 2021).
infection (9 papers, 2016 to 2025). The state of being infected such as from the introduction of a foreign agent such as serum, vaccine, antigenic substance or organism. "A possible hypothesis is that increased preconditioning IL-31 levels reflect disturbed epithelial barriers (e.g., skin, airways, and gastrointestinal tract) that cause a long-lasting predisposition to inflammation and/or infection." (PMID 27809289, 2016). "In our study, IL-31 expression was significantly increased at weeks 2 and 12 post-infection (P < 0.05), which supports the idea that IL-31 plays a role in scabies-related itch." (PMID 41325491, 2025). "Comparing cytokine levels between patients with primary and secondary DENV infections, we observed that IL-2, IL-6, IL-31, and IL-12p70 were significantly higher in primary infection and MIP1β was significantly higher in secondary infection." (PMID 35631079, 2022). "However, at 3 months, increased fold change of cytokines IL‐31 (P = 0.0135) and IL‐10 (P = 0.0365) were correlated with subsequent infection." (PMID 40766049, 2025). "IL-31 expression was increased at weeks 2 and 12 post-infection (P < 0.05)." (PMID 41325491, 2025). "Upon further investigation, we found that specific cytokines, chemokines and growth factors could be correlated with subsequent infection: IL‐10, IL‐31, ENA‐78, fractalkine, MCP‐2, HGF and MMP‐1." (PMID 40766049, 2025). "An in vitro study showed that infection with Porphyrormonas (P.)gingivalis increased the expression of the IL-31 receptor (IL-31R) in human gingival epithelial cells and that IL-31 in those cells downregulates the P. gingivalis-induced overexpression of claudin-1." (PMID 37958576, 2023). "AAV8‐IL‐31, but not AAV8‐vector, infection successfully restored IL‐31 expression in the livers of IL‐31ΔHep mice at months 6 and 10 post‐DEN." (PMID 37733361, 2021). "The infection of AAV8‐IL‐31, but not AAV8‐vector, increased Pou2f2 mRNA and induced POU2F2+ hepatocytes development at months 6 and 10 post‐DEN, suggesting that hepatic IL‐31 recovery restores Pou2f2 expression." (PMID 37733361, 2021).
inflammation (5 papers, 2015 to 2025). Aberrant reaction of the microcirculation characterized by movement of fluid and leukocytes from the blood into extravascular tissues. "On the other hand, the protective role of IL-31 against Th2-lung inflammation has been demonstrated in several studies." (PMID 35742951, 2022). "Consistent with other reports, this study demonstrates that IL‐31/IL‐31RA interactions protect against allergen‐induced local lung inflammation." (PMID 32648940, 2021). "Thus, our data indicate that IL‐31 signaling regulates allergen‐induced lung inflammation." (PMID 32648940, 2021). "In addition, IL-31 in humans has been shown to stimulate the secretion of other proinflammatory cytokines (IL-4, IL-6, IL-8, IL-13, IL-16, IL32) as well as chemokines and matrix metalloproteinases from other tissues, which suggests IL-31 plays an active role in chronic inflammation." (PMID 40133889, 2025). "Also, IL-31 alone or in combination with IL4 or IL-13 could elevate the expression of epidermal growth factor (EGF), vascular endothelial growth factor (VEGF) and monocyte chemoattractant protein-1 (MCP-1/CCL2) from human bronchial epithelial BEAS-2B cells, which contribute to airway inflammation." (PMID 30647024, 2019).
cardiovascular diseases (4 papers, 2021 to 2025). "In summary, our results revealed a novel mechanism that transcriptional and epigenetic regulation of miR‐195‐3p inhibits macrophage inflammation through targeting IL‐31, which provides a candidate diagnostic marker and novel therapeutic target in cardiovascular diseases induced by Hcy." (PMID 34592792, 2021). "This review discusses the current understanding of the role of these recently identified interleukins, such as IL-27, IL-31, IL-32, IL-33, and the IL-28 group (IL-28A, IL-28B, IL-29), in the development of cardiovascular diseases." (PMID 39844544, 2025). "While direct evidence of IL-31's role in cardiovascular disease is limited, there is growing interest in understanding its potential mechanisms in these conditions." (PMID 39844544, 2025). "Although IL-31 belongs to the IL-6 family, its role in cardiovascular diseases is not well understood." (PMID 39844544, 2025). "By regulating STAT3 and MAPK signaling pathways, IL-31 might contribute to vascular remodeling and inflammation, which are key factors in cardiovascular disease progression." (PMID 39844544, 2025).
hematological malignancies (4 papers, 2015 to 2023). "Among hematological diseases, we have found that the role of IL-31 was mainly studied in CTLC." (PMID 35742951, 2022).
neurological disease (2 papers, 2022 to 2023). "The trend of these articles shows that the interest in Il-31 has significantly increased in the last five years, in various fields of medicine, such as rheumatological diseases, neurological diseases, and other itchy-skin conditions." (PMID 35742951, 2022).
immune dysfunctions (1 paper, 2023). "Altogether, our data indicate elevated contents of inflammatory cytokines TNF-α, IL-4, IL-21, BAFF, IL-31, IL-5 and APRIL in CSF samples from ASD patients, suggesting the potential inflammatory conditions and immune dysfunctions that might contribute the pathogenesis and progression of this disease." (PMID 38114596, 2023).
infectious disease (1 paper, 2022). A disorder directly resulting from the presence and activity of a microbial, viral, or parasitic agent in humans. "Another field in which the recent studies delved in to research the role of IL-31 has been infectious diseases." (PMID 35742951, 2022).
neurodegenerative disease (1 paper, 2020). A disorder of the central nervous system characterized by gradual and progressive loss of neural tissue and neurologic function. "Collectively, the study suggested that apigenin and luteolin’s regulation of signaling pathways contributed to the inhibition of IL-31 and IL-33, thus suggesting its importance for the improvement of neurodegenerative diseases involving these two cytokines." (PMID 32204450, 2020).
psychiatric disorder (1 paper, 2021). A disorder characterized by behavioral and/or psychological abnormalities, often accompanied by physical symptoms. "A recent theory highlights the role of the IL-33/IL-31 axis in different autoimmune disorders; immune system impairment as a comorbidity in psychiatric disorders was reported by several authors." (PMID 33810498, 2021).
IL31 also shares sentences with these, for which no sentence is quoted: allergies (6 papers); rhinitis (5); Crohn disease (4); lichen planus (3); myeloproliferative disorder (3); prurigo (3); autoimmune disorder (2); Behçet’s disease (2); heart disease (2); heart failure (2); liver fibrosis (2); ovarian cancer (2); rheumatoid arthritis (2); Sézary syndrome (2); allergic respiratory disease (1); angioedema (1); arteritis (1); B-cell lymphomas (1); bladder squamous cell carcinoma (1); brain hemorrhage (1); chronic hepatitis (1); chronic hepatitis B virus infection (1); chronic periodontitis (1); combined immunodeficiency (1); connective tissue diseases (1); depression (1); diabetic retinopathy (1); eosinophilia (1); essential thrombocythemia (1); glioblastoma (1).
A further 46 diseases each share a sentence with IL31 in 1 paper.